STAT3 (signal transducer and activator of transcription 3)
Diseases named in the same sentence as STAT3 in open-access papers (continued):
Sharing a sentence is not in itself a finding about the gene and the disease.
pancreatic cancer (continued). "A PDGFβ-specific inhibitor, TKI258, reduces the PDGF-β-induced increase in STAT3 phosphorylation in MiaPaCa2 pancreatic cancer cells and endothelial cells." (PMID 34122447, 2021). "AKT1, CDKN2A, ERBB2, and IL6 are common protein core of liver and pancreatic cancers, while STAT3, CASP3, NOTCH1, and CTNNB1 are possible differential proteins to discriminate these cancers." (PMID 35154607, 2021). "IL-6 activated the JAK2/STAT3 pathway, which accelerated cell cycle progression by promoting CyclinD1 expression in pancreatic cancer." (PMID 34165442, 2021). "This study shows that activation of the P2X7R in PSCs leads to IL-6 release into the TME and subsequent activation of STAT3 signaling in pancreatic cancer cells." (PMID 34440697, 2021). "Previous studies have shown that “basal” IL-6 released from PSCs plays a leading role in activating the JAK/STAT3 pathway in pancreatic cancer cells." (PMID 34440697, 2021). "Our data in monolayer, 3D co‐culture, and in vivo all strongly point towards dual targeting of Ref‐1 and STAT3 to being deleterious to pancreatic cancer cells, when appropriate combinations are used." (PMID 33274592, 2021). "These cells provide genetic evidence that the inhibition of both STAT3 signalling in concert with Ref‐1 signalling is lethal to pancreatic cancer cells." (PMID 33274592, 2021). "IL-6/STAT3 signaling can promote pancreatic cancer growth and metastasis, which induce suppressor of cytokine signaling 3 (SOCS3) methylation through DNA methyltransferase 1 (DNMT1)." (PMID 33406733, 2021). "In the presented gene regulatory network, the next protein being activated in the transition towards pancreatic cancer after CFL1 is STAT3 (time step 8)." (PMID 33578795, 2021). "An increasing number of studies have shown that STAT3 activation plays a pivotal role in the progression, metastasis, and drug resistance of pancreatic cancer." (PMID 34834023, 2021). "A recent paper reported that DHA promotes the cell apoptosis of PANC-1 pancreatic cancer cells by inducing DNA fragmentation, activating caspase-3, and increasing the ratio of Bax/Bcl-2 via downregulating STAT3/nuclear factor (NF)-κB/cyclin D1 signaling." (PMID 33801246, 2021). "The current results indicate that AKT1, CDKN2A, ERBB2, and IL6 are the common protein core of liver and pancreatic cancers, and STAT3, CASP3, NOTCH1, and CTNNB1 are possible differential proteins that discriminate these cancers." (PMID 35154607, 2021). "This led to inhibited STAT3 phosphorylation and suppressed growth of pancreatic cancer cells with intact IL-6/gp130 signaling in both in vitro and in vivo settings." (PMID 34149710, 2021). "While in pancreatic cancer cells, apoptosis induced due to andrographolide treatment was due to STAT3 and Akt pathway activation." (PMID 33815659, 2021). "Overall, pancreatic tumours grown in the presence of CAFs were sensitized to the combination of STAT3 and Ref‐1 inhibition in vivo." (PMID 33274592, 2021). "Overall, various cancer cell lines consistently responded to combination inhibition of STAT3 signalling and Ref‐1 with additivity or synergy when compared to STAT3 inhibition alone, especially in pancreatic cancer cell lines." (PMID 33274592, 2021). "Herein, the H19/miR-675-3p/SOCS5/STAT3 axis plays an important role in pancreatic cancer cells, which revealed potential targets for the treatment of pancreatic cancer." (PMID 34977037, 2021). "In turn, IL-6 released from PSCs stimulates STAT3 activation in pancreatic cancer cells, indicating that the P2X7R is an important factor in the PSC-cancer cell crosstalk." (PMID 34440697, 2021). "On the other hand, gp130/STAT3-dependent secretion of SAA proteins by hepatocytes promoted metastatic colonisation of pancreatic cancer cells in the liver." (PMID 34047814, 2021). "Inhibition of these pathway components, particularly STAT3, is therefore considered a promising option for the treatment of pancreatic cancer." (PMID 33546207, 2021).
pancreatic cancer (continued). "STAT3 is constitutively activated in pancreatic cancer via phosphorylation of Tyr705, as found in human tumor specimens as well as in various pancreatic cancer cell lines." (PMID 34834023, 2021). "CRP is also reported to increase the malignant properties of pancreatic cancer cells through upregulation of the ERK/AKT/STAT3 pathway." (PMID 33801202, 2021). "Formerly, we have demonstrated that dual targeting of Ref‐1 (redox factor‐1) and STAT3 is synergistic and decreases cell viability in pancreatic cancer cells." (PMID 33274592, 2021). "Our data establish N4 as a STAT3 inhibitor that has potential therapeutic value for pancreatic cancer." (PMID 33420372, 2021). "IL-6 from CAFs inhibits NK cell activity, and activates signal transducer and activator of transcription 3 (STAT3) in pancreatic cancer cells." (PMID 33572223, 2021). "CD147 can promote STAT3-mediated pancreatic cancer development by interacting with CD44s18 and we found that CD44s colocalized with CD147 in CRC cells." (PMID 34262017, 2021). "Morusin specifically inhibited constitutive STAT3 activation both at tyrosine residue 705 and serine residue 727 in four pancreatic tumor cells." (PMID 34578920, 2021). "Down-regulation of TYRO3 via RNAi in breast, colon, head and neck and pancreatic cancers has been reported to regulate the cellular signaling pathway by reducing the phosphorylation of STAT3, AKT, and ERK." (PMID 34721022, 2021). "The silencing of IL4Rα inhibited the growth and invasiveness of pancreatic cancer cells by suppressing the STAT3 and Akt pathways." (PMID 33419470, 2021). "Our data demonstrated that N4 was a potential STAT3 inhibitor and it inhibited STAT3 activation in pancreatic cancer." (PMID 33420372, 2021). "The Stattic, C188-9 and BP-1-102 were the established STAT3 inhibitors, while, N4 exhibited more potency in suppressing pancreatic cancer growth and STAT3 signaling in vitro and in vivo." (PMID 33420372, 2021). "It was also reported that EGCG has a significant anticancer effect on pancreatic cancer, partly by inhibiting the STAT3 signaling pathway." (PMID 34564613, 2021). "TAMs secrete CXCL8 to promote pancreatic cancer cell migration and invasion through the signal transducer and activator of transcription 3 (STAT3) pathway." (PMID 35011369, 2021). "The key role of STAT3 in promoting pancreatic cancer progression has been proven, but effective interventions that suppress STAT3 activities are limited." (PMID 33420372, 2021). "While this work highlighted a paracrine role of LIF produced by stellate cells on cancer cell differentiation and epithelial-mesenchymal transition, it should be noted that pancreatic cancer cell lines express active STAT3." (PMID 34491463, 2021). "ECM remodelling, epithelial-mesenchymal transition (EMT) and JAK/STAT3 pathway-dependent genes transcription in pancreatic cancer cells are three primary mechanisms responsible for the maintenance of PDAC growth, invasion and metastatization." (PMID 33630157, 2021). "The current findings indicate that STAT3 and CASP3 are related to liver cancer, while NOTCH1 and CTNNB1 are associated with pancreatic cancer." (PMID 35154607, 2021). "STAT3 is a central transcription factor in the progression of pancreatic cancer, which can promote the transcription of multiple genes encoding proliferation-related proteins, such as Cyclin D1." (PMID 34858184, 2021). "Curcumin also inhibits phosphorylation STAT-1, STAT-3, and Notch signaling pathways which are responsible for pancreatic cancer cell growth." (PMID 34483905, 2021). "The negative regulation of STAT3 by miR-20a via binding to the 3′-UTR of STAT3 mRNA was also demonstrated in pancreatic carcinoma cells." (PMID 34071096, 2021). "Among them, EGCG has been reported to reduce STAT3 phosphorylation in head and neck carcinomas and pancreatic cancer." (PMID 32438613, 2020).
pancreatic cancer (continued). "Previous studies have reported that aberrant activation of signal transducers and activators of transcription 3 (STAT3) is involved in oncogenesis in diverse types of human cancer including pancreatic cancer cells." (PMID 32422890, 2020). "Dhillon and the co-workers reported clinical response of curcumin to repress phosphorylation of constitutive STAT3 by daily oral administration in pancreatic cancer patients." (PMID 32891174, 2020). "Some reports have demonstrated that STAT3 inhibition decreases both radiation resistance and stem cell numbers in pancreatic cancer." (PMID 32823915, 2020). "It was reported to be a potent inhibitor of cell proliferation on pancreatic cancer cell lines through apoptosis induction, regulation of the signal transducer and activator of transcription 3 (STAT3) signaling pathway, and G0/G1 cell cycle arrest." (PMID 32903500, 2020). "The results of bioinformatics analysis suggested that JAK2/STAT3 signaling was activated in pancreatic cancer tissues." (PMID 33029256, 2020). "STAT3 activation has also been reported to promote PanIN formation in an oncogenic Kras mouse model, showing the importance of STAT3 in the development of pancreatic cancer." (PMID 32609742, 2020). "Of note, an in vivo mouse model of PC mimic obesity/T2DM demonstrated that metformin reduced desmoplasia in pancreatic tumor by directly inhibiting the AT1/TGF-β/STAT3 signaling and reducing release of collagen-I/HA by PSCs." (PMID 32659999, 2020). "As shown in previous studies, WP1066 inhibits proliferation and induces apoptosis of pancreatic cancer cells, reduces the expression of STAT3-dependent anti-apoptotic proteins (Bcl-xL, survivin), and blocks constitutive and IL-6-induced STAT3 phosphorylation." (PMID 33158194, 2020). "It should be emphasized that the high activity of STAT3 is also one of the main mechanisms of pancreatic cancer cell proliferation." (PMID 33158194, 2020). "Studies have shown that activation of STAT3 in ovarian cancer leads to upregulation of MMP2 expression, and inhibition of STAT3 in pancreatic cancer cells results in down-regulation of MMP9 expression." (PMID 33292347, 2020). "Previous study has shown that STAT3 plays a critical role in cell apoptosis, metastasis, proliferation, and immunomodulation in cancer cells including pancreatic cancer." (PMID 32422890, 2020). "Our findings demonstrate that sulforaphane promotes T-cell activation by dendritic cells through the modulation of regulatory molecules, JAK/STAT3- and microRNA-signaling in healthy conditions and in context of pancreatic cancer-derived antigens." (PMID 33193420, 2020). "Conversely, AdipoRon, a small molecule agonist for both adiponectin receptors, induced PC cell apoptosis and reduced pancreatic tumor growth, presumably via downregulation of the leptin/STAT3 signaling." (PMID 32659999, 2020). "AnxA1 induces invasiveness, drug-resistance, and generation of CSCs in prostate and pancreatic cancer by increasing the p-STAT3 level." (PMID 31952344, 2020). "USP5 overexpression is critical in both pancreatic cancer progression and metastasis via enhancing STAT3 signaling." (PMID 33123271, 2020). "As a transcription factor, STAT3 is an important regulator in various cancer cells including pancreatic cancer cells." (PMID 32422890, 2020). "Using would healing assays, Transwell assay, and immunoblotting analysis, we demonstrated that STAT3 downregulation significantly impaired co-cultured CM-induced pancreatic cancer cell migration, invasion, and EMT." (PMID 32308766, 2020). "Hyperactivated STAT3 promotes the growth of pancreatic cancer, metastasis, initiation, drug resistance, and remodeling of the tumor microenvironment and is associated with patient survival." (PMID 32457835, 2020). "We next evaluated if the enrichment of CD133 + population, as well as the metabolic changes observed in pancreatic cancer cells, were dependent on activation of STAT3." (PMID 33177492, 2020).
pancreatic cancer (continued). "Luteolin treatment in a dose-dependent manner inhibited EMT, protein expression of MMPs (i.e., MMP2/7/9), and STAT3 signaling, as well as decreased the invasiveness of pancreatic cancer cells." (PMID 32717779, 2020). "STAT3 is involved in various stages of pancreatic cancer, and given its role in driving PDAC progression, it is considered an important therapeutic target." (PMID 32824207, 2020). "Preclinical data have confirmed that STAT3 signaling pathway is pivotal in the development of many human cancers including pancreatic cancer." (PMID 32457835, 2020). "Taken together, these results suggested a vital role for STAT3 signaling in SC-derived IL6-induced pancreatic cancer cell migration and invasion." (PMID 32308766, 2020). "IL-6/STAT3 signaling pathway was demonstrated to inhibit autophagy in U937 cells, while it activated this process in pancreatic cancer cells." (PMID 31598806, 2020). "Morusin also targets the STAT3 pathway and its downstream targets, including survivin, cyclin B1, to exert antitumor activity in prostate and pancreatic cancers." (PMID 32906784, 2020). "To determine this, we stimulated pancreatic cancer cells with IL6 in the presence of a STAT3 inhibitor Stattic." (PMID 33177492, 2020). "PAK4, a dual Cdc42/Rac1 effector, is overexpressed in pancreatic CSCs and functions as an upstream activator of STAT3, which is required for pancreatic cancer stemness." (PMID 32915198, 2020). "Another pseudokinase, Sgk223 (Pragmin), promotes invasion and EMT in pancreatic cancer via activation of JAK1/STAT3 by the formation of Sgk223-STAT3 complex." (PMID 31952344, 2020). "A recent study has shown that ITGA2 increases the expression of PD-L1 by activating the STAT3 pathway in pancreatic cancer." (PMID 32899691, 2020). "In pancreatic carcinoma cells, cryptotanshinone repressed STAT3 phosphorylation via a mechanism autonomous of JAK2 phosphorylation." (PMID 32545187, 2020). "More specifically, oral administration of 12 μM BITC suppressed new vessel formation and suppressed pancreatic tumour growth in mice through inhibition of STAT3 phosphorylation." (PMID 31003534, 2019). "Subsequently, it inhibits STAT3 phosphorylation and transcription induced by IL6, causing apoptosis, blocking cell migration in pancreatic cancer cells and suppressing tumor growth." (PMID 31139333, 2019). "In another report, BT was found to activate JNK and p38 MAPK pathways with concurrent inhibition of proinflammatory signaling pathways such as NF-κB and STAT3 in pancreatic cancer cells." (PMID 31575007, 2019). "Bazedoxifene, a selective estrogen receptor modulator, has been proven to be an effective GP130/STAT3 signaling inhibitor, inhibiting growth and migration of pancreatic cancer cells in animal studies." (PMID 31139333, 2019). "Although we believe that our results add valuable insights into the role STAT3 in pancreatic cancer, we note a few limitations present in this study." (PMID 31796877, 2019). "Lastly, we observed that STAT3 target genes were more highly expressed in primary pancreatic cancer tissue, compared to pancreatic cancer cell lines." (PMID 31796877, 2019). "To further validate our STAT3 inferences, we compared normal pancreatic to pancreatic tumor tissue, expecting that only tumor tissue should show high STAT3 activities." (PMID 31796877, 2019). "We further detected the role of STAT3 in the acquired migration and invasion of pancreatic cancer induced by gemcitabine and VPA." (PMID 31244991, 2019). "In summary, crosstalk between macrophages and pancreatic cancer cells through the upregulation of CD59 in an IL-6R/STAT3 manner protects pancreatic cancer from CDC." (PMID 31685825, 2019). "Taken together, our results suggest that ROS stimulates the activation of AKT and STAT3, and the migration and invasion of pancreatic cancer cells induced by gemcitabine and low-dose VPA." (PMID 31244991, 2019).
pancreatic cancer (continued). "Our results suggest that, even though IL-6 and LIF share STAT3 as a downstream effector, they have distinct functional roles in human pancreatic cancer cells harboring mutant KRAS." (PMID 31296870, 2019). "Transcription factor (TF) STAT3 contributes to pancreatic cancer progression through its regulatory roles in both tumor cells and the tumor microenvironment (TME)." (PMID 31796877, 2019). "Several studies have shown that CuB inhibits STAT3 signaling in various cancer models such as colorectal cancer, lung cancer, neuroblastoma, acute myeloid leukemia, pancreatic cancer and breast cancer." (PMID 31600949, 2019). "Experimental studies have shown that the IL6/GP130/STAT3 pathway is involved in pancreatic cancer tumorigenesis and progression as well as in the development of other tumors." (PMID 31139333, 2019). "The STAT3 signaling pathway plays an important role in the progression of chemoresistance among pancreatic cancer cells." (PMID 31244991, 2019). "We further evaluated STAT3 expression in tumor samples compared to normal pancreatic tissue and observed significant up-regulation of STAT3 expression in pancreatic cancer (p = 2E-7), consistent with previous reports." (PMID 31796877, 2019). "The combination of STAT3 knockdown and gemcitabine can restore sensitivity to gemcitabine in pancreatic cancer cell line by inducing proapoptotic signals and increasing the cell population in G1 cell cycle arrest." (PMID 31319622, 2019). "A similar observation was noted in pancreatic cancer cells, where after suppressing STAT3 expression using STAT3 short hairpin RNA (shRNA) expression vectors, the malignancy and metastasis of pancreatic cancer cells remarkably reduced." (PMID 31569687, 2019). "• Exogenous Reg3A notably enhanced the STAT3 activation by phosphorylation in pancreatic cancer MiaPaCa2 and Panc1 cells." (PMID 31921694, 2019). "We have demonstrated that piperlongumine inhibits STAT3 and its activation to suppress anoikis resistance resulting in inhibition of metastatic potential of pancreatic cancer and melanoma." (PMID 31600949, 2019). "Collectively, we show that our framework can be utilized to obtain biological insights and that the distinction between E- and T-STAT3 is crucial when investigating STAT3 in pancreatic cancer." (PMID 31796877, 2019). "NOS inhibitor treatment significantly suppressed STAT3 S-nitrosylation, promoted STAT3 phosphorylation and enhanced viability of pancreatic cancer cells, further indicating the essential roles of S-nitrosylation in PDAC pathogenesis." (PMID 31801946, 2019). "Here, we suggest that pancreatic cancer-educated macrophages induce the upregulation of CD59 in an IL-6R/STAT3-dependent manner in pancreatic cancer cells." (PMID 31685825, 2019). "We have also demonstrated that BITC suppresses angiogenesis and invasion in pancreatic tumors by inhibiting STAT3 mediated HIF-1α/VEGF/Rho-GTPases." (PMID 31600949, 2019). "In particular, STAT3 was identified as one of the TFs with higher expression levels in TME than in pancreatic cancer cells." (PMID 31796877, 2019). "Consistently, deletion of RAGE expression in pancreatic cancer cells leads to downregulated IL-6 expression, STAT3 localization to mitochondria, as well as the downregulation of the upstream signaling pathways such as phosphorylation of Jak1 and Src." (PMID 29474476, 2018). "Mackenzie and coworkers demonstrated the importance of targeting mitochondrial STAT3 in pancreatic cancer." (PMID 29914167, 2018). "For pancreatic cancer cells, STAT3 is constitutively expressed in pancreatic cancer cells, which activates the expression of VEGF for angiogenesis." (PMID 30060755, 2018). "Altogether, our results indicate that TGF-βRII signalling implicates STAT3 and c-Jun phosphorylation in pancreatic cancer cells." (PMID 30065235, 2018).